CTLA4 (cytotoxic T-lymphocyte associated protein 4)
Diseases named in the same sentence as CTLA4 in open-access papers (continued):
Sharing a sentence is not in itself a finding about the gene and the disease.
tumor (continued). "Tumor-infiltrating T cells with upregulated expression of activation markers, such as CD44, CD69, and CD25, and downregulated expression of exhaustion markers like PD-1 and CTLA-4 indicate a higher T-cell functional status that mediates a stronger and more enduring anti-tumor response." (PMID 40867322, 2025). "For instance, ECM glycoprotein alterations may foster a tumor-supportive niche, while immune dysregulation—marked by upregulated checkpoint molecules such as PD-L1 and CTLA-4—could enable tumor cells to escape immune surveillance." (PMID 40299498, 2025). "Moreover, the addition of CTLA-4 blockade antibodies during the initial phase of TIL culture resulted in more effective anti-tumor TILs than standard TIL culture." (PMID 40369674, 2025). "Modulating the microbiota—particularly within the gut and tumor microenvironment—may also influence responses to cancer therapies, including chemotherapy and immune checkpoint blockade (PD-1, CTLA-4)." (PMID 40723356, 2025). "We propose that while the direct killing of TREG, mediated by anti-CTLA-4 antibodies, is the primary mechanism through which they exert their anti-tumour effects, selective blockade of sCTLA-4 contributes to ‘releasing the brakes’ of the antigen-specific immune response." (PMID 40265076, 2025). "Combination therapies involving Mg2+ modulators (e.g.: ionophores) with anti-PD-1/CTLA-4 agents could reverse the “cold” tumor phenotype, whereas Mg2+ chelators (e.g.: EDTA) might improve chemotherapy sensitivity." (PMID 41174507, 2025). "CTLA-4 is a negative regulator of T cells activation, which improves regulatory T cells (Tregs)-mediated immunosuppression by suppressing CTLs immune function, eventually inducing tumor immune escape and drug resistance." (PMID 40296912, 2025). "Recently, immunotherapy based on the inhibition of immune checkpoint (IC) molecules, most notably of the programmed cell death receptor (PD)-1 and cytotoxic T lymphocyte antigen (CTLA)-4, has shown potential to enhance immune response against tumor cells and thereby modulate TME." (PMID 40940764, 2025). "The combination of TH-302, a hypoxia-activated prodrug that reverses hypoxia, with PD-1 and CTLA-4 inhibitors may improve survival in mouse tumours as compared to TH-302 alone or dual antibody alone." (PMID 40647497, 2025). "Individual reports indicate that a variety of tumor cells express endogenous CTLA4." (PMID 39404738, 2025). "CTLA-4 suppresses dendritic cell maturation and function by activating the extracellular signal–regulated kinase (ERK; encoded by MAPK1) and STAT3 pathways, which impairs T cell activation and anti-tumor immunity." (PMID 41550427, 2025). "Similarly, CTLA-4 inhibitors operate in the same manner, thereby promoting anti-tumor immune responses." (PMID 40963868, 2025). "Additionally, there is a high level of immune cell infiltration in the anti-PD-1 + TIGIT-treated tumour tissue sections with a decreased level of PD-L1 expression when compared to anti-PD-1 + CTLA-4-treated or PBS control-treated tumour tissue sections." (PMID 39939955, 2025). "Moreover, Tregs, a subset of CD4+ T cells, are the primary targets of anti-CTLA-4 for anti-tumor efficacy." (PMID 40861801, 2025). "Chiefly, CTLA-4 and PD-1 located on T cells, and PD-L1 located on tumor cells act as inhibitors of the immune response, generating T cell apoptosis and depletion, in addition to a decreased cytotoxic activity on tumor cells." (PMID 41010821, 2025). "A CTLA-4 blockade can inhibit tumor formation, making it useful in treating malignancies 39273605." (PMID 39941799, 2025). "Immune checkpoint molecules—such as programmed cell death protein 1 (PD-1), its ligand PD-L1, cytotoxic T-lymphocyte-associated antigen 4 (CTLA-4), and T-cell immunoglobulin and mucin-domain containing-3 (TIM-3)—play pivotal roles in suppressing anti-tumor immunity." (PMID 40771805, 2025).
tumor (continued). "While their SWNTs combined with PTT failed to fully inhibit the growth of a simulated metastasis, the team found that the addition of anti-CTLA-4 enhanced their treatment leading to significant inhibition of the secondary tumor and increased survival in their murine model." (PMID 41180369, 2025). "For example, preliminary evidence suggests that in the setting of anti-cytotoxic T-lymphocyte associated protein 4 (CTLA-4) or anti-PD-1 therapy, TLS gene expression may occur independently of the tumor’s mutational status." (PMID 40940789, 2025). "This process strengthens the immune response against neoplasms and specifically targets immune checkpoint proteins such as PD-1 and its ligands (PD-L1 and PD-L2), as well as other targets such as CTLA-4, to enhance the anti-tumor effects of T cells, preventing them from attacking cancer cells." (PMID 40943055, 2025). "Notably, the activation of immune checkpoint pathways, such as PD-1/PD-L1 and CTLA-4, enables tumor cells to suppress T cell-mediated anti-tumor responses, thereby supporting their survival." (PMID 40094019, 2025). "However, tumors exploit these pathways by aberrantly upregulating immune checkpoint molecules (e.g., CTLA-4 and PD-1 on T cells) or their ligands (e.g., PD-L1 on tumor cells), thereby dampening antitumor immunity." (PMID 40474230, 2025). "Moreover, the absence of ICOS led to a significant reduction in anti-tumour T-cell responses triggered by the anti-CTLA-4 antibody, thereby hindering tumour rejection." (PMID 39325360, 2025). "Anti-CTLA-4 may exert its anti-tumor effects by increasing the activity of effector CD4+ T cells and inhibiting the Tregs-dependent immune suppression." (PMID 40861801, 2025). "CTLA-4 is expressed by Tregs, other T-cells, and even by tumor cells in the TME." (PMID 40507214, 2025). "upregulation of PD-1, CTLA-4, and other inhibitory molecules is a key mechanism of T cell depletion, and metabolic reprogramming and chronic antigenic stimulation further weaken the anti-tumor activity of T cells." (PMID 41098737, 2025). "While exhaustion markers, such as PD-1 and CTLA-4, remained stably expressed across tumor progression, co-stimulatory molecules, including CD28 and ICOS, were significantly downregulated by 6 weeks, highlighting a state of persistent checkpoint signaling coupled with a loss of co-stimulation." (PMID 41278869, 2025). "Interestingly, they found that while CTLA4 was localized to the membranes of lymphocytes, the CTLA4 found in tumor cells appeared to be of the soluble isoform." (PMID 40523912, 2025). "However, its prognostic significance in disease remains uncertain, with limited studies investigating CTLA‐4 levels at tumour sites." (PMID 40415479, 2025). "Moreover, CD8+ tumor-infiltrating T cells enhance the expression of PD-1 and CTLA-4 in patients with pancreatic ductal adenocarcinoma (PDAC)." (PMID 40078367, 2025). "Targeting this pathway, for example, by inhibiting miR-155 in Tregs, could restore Treg CTLA-4 and potentially alter the balance in favor of anti-tumor immunity." (PMID 40647470, 2025). "Tumor cells exploit molecules like PD-1, CTLA-4, and LAG-3 to suppress cytotoxic immune responses." (PMID 41244711, 2025). "Tumor cells may also use these mechanisms to upregulate other immune checkpoint molecules, such as CTLA-4 or TIM-3." (PMID 40564180, 2025). "Our data indicate that CCDC8 may contribute to an immunosuppressive microenvironment, as evidenced by the upregulation of immune checkpoint molecules like PD-1, PD-L1, and CTLA-4, which are known to inhibit T cell function and facilitate tumor immune escape." (PMID 39744495, 2025). "Additionally, trials combining RT with a dual checkpoint blockade (e.g., anti-CTLA4 and anti-PD-1/PD-L1) have shown promise in overcoming resistance by modulating the tumor microenvironment and reversing T-cell exhaustion." (PMID 40867277, 2025).
tumor (continued). "In addition, tumor-promoting M2 polarization was more common, and immune-suppressed checkpoints like CTLA-4 presented higher expression in diffuse-type tumors." (PMID 40777025, 2025). "Immune-checkpoint blockade (ICB) drugs such as antibodies against programmed cell death 1 (PD-1), programmed death ligand 1 (PD-L1) or cytotoxic T-lymphocyte-associated antigen 4 (CTLA-4) (respectively, anti-PD-1, anti-PD-L1 and anti-CTLA-4) aim to reinvigorate tumour-infiltrating CD8+ T cells." (PMID 40065102, 2025). "CTLA-4 blockade enhances priming and expansion of tumor-reactive T cells." (PMID 40621467, 2025). "Additionally, the inhibition of CD73 improves the efficacy of anti-PD-1 and anti-CTLA-4 monoclonal antibodies, inhibits tumour growth, and reverses the exhausted T cell phenotype in mouse models." (PMID 40149368, 2025). "Tumor exosomes carrying CTLA-4 suppress T cell activity and promote tumor growth." (PMID 40227747, 2025). "ICIs enhances the anti-tumor activity of the immune system by inhibiting immune downregulating factors such as programmed cell death receptor 1 (PD-1), programmed cell death ligand 1 (PD-L1), and cytotoxic T lymphocyte antigen 4 (CTLA-4)." (PMID 39664382, 2024). "This aptamer forms a highly stable circular structure and comprises a CTLA-4 aptamer and a PD-L1 aptamer, serving as an immune checkpoint inhibitor by concurrently blocking the CTLA-4/B7 and PD-1/PD-L1 signaling pathways to enhance the anti-tumor immune response." (PMID 38735927, 2024). "Variants in genes like CTLA-4, ERCC3, and TNF-α might impact immune regulation and inflammatory responses, crucial in tumor microenvironment dynamics." (PMID 38360742, 2024). "Detailed studies on the mechanisms of immune checkpoints have shown that ICIs such as CTLA-4 and PD-1/PD-L1 exhibit effective anti-tumor activity in malignancies such as urothelial carcinoma, renal cell carcinoma, Hodgkin lymphoma, non-small-cell lung cancer, and melanoma." (PMID 39200350, 2024). "This was also demonstrated in another clinical analysis of sarcomas, where the killing of tumor cells by CD8+ T cells was often blocked by immune checkpoints on the tumor, such as PD-L1 and CTLA-4, and in recent years there has been a flurry of activity regarding ICB therapies." (PMID 39916962, 2024). "Interestingly, research has also found NK cells can reduce their IFNγ production via up-regulation of CTLA4, which is accompanied by tumor development, thereby promoting tumor progression." (PMID 38244071, 2024). "Interfering with the PD-1/PD-L1 immune checkpoint showed superior clinical benefit compared to CTLA-4 blockade, which might be due to the less restricted expression pattern of PD-1 and its ligands, particularly PD-L1 in tumor cells." (PMID 38573347, 2024). "Thus, anti-CTLA-4 and anti-PD-1 mAbs restore anti-tumor activity by facilitating the differentiation or the reactivation of tumor-reactive cytotoxic CD8+ T cells and of helper CD4+ T cells." (PMID 38318190, 2024). "The overexpression of CTLA-4 on Tregs helps to dampen anti-tumor immunity." (PMID 38927907, 2024). "CTLA-4 inhibition by monoclonal antibodies may induce tumor rejection through direct blockade of CTLA-4 competition for CD-80 (B7-1) and CD-86 (B7-2) ligands, which enhances CD28 co-stimulation." (PMID 39091917, 2024). "Nivolumab and ipilimumab, two ICIs that target CTLA-4 and PD-1, induce T cell activation and cause tumor cells death by binding to B7 ligands CD80 and CD86 expressed on antigen-presenting cells (APCs) and PD-L1 on either tumor cells or APCs, respectively." (PMID 38443363, 2024). "Moreover, interactions between immune checkpoints and their ligands (e.g., PD-1/PD-L1 and CTLA-4/CD86) are further involved in the metabolic reprogramming of tumor cells and immune cells." (PMID 38361757, 2024). "Thus, down‐regulation of genes related to poor prognosis correlated well with improved tumor control seen in APG‐157 + anti‐CTLA‐4 antibody group." (PMID 38686626, 2024).
tumor (continued). "CTLA-4 is recognized as a negative regulator of anti-tumor immunity." (PMID 39200350, 2024). "Moreover, CTLA-4 expression, while predominantly described in T cells, has also been observed in a variety of cell types, including tumor cells, DCs, and other cells of lymphoid and myeloid lineages." (PMID 39684559, 2024). "Indeed, in vivo administration of anti-CTLA-4 antibody suppressed tumor growth and generated immunological memory after secondary tumor rechallenge." (PMID 39247203, 2024). "Research results showed that although the combination of MIO and immune ICIs (anti-PD-1 and anti CTLA-4 antibodies) reduced tumor volume in 4T1-luciferase cell-implanted BALB/c mice as compared to the control group, there was no improvement in the overall survival of mice with the treatment." (PMID 38893132, 2024). "At the same time, combination therapy with PD-1/PD-L1 and CTLA-4 blocking antibodies may provide synergistic anti-tumor benefits for dMMR/MSI-H mCRC patients." (PMID 38918278, 2024). "Accordingly, our patient could initially have had a cold tumor microenvironment characterized by low immune infiltration, which would have been transformed into a hot tumor by the anti-CTLA-4 treatment." (PMID 39451738, 2024). "In patients with urothelial carcinoma, combined treatment with PD-1 and CTLA-4 before tumor resection significantly increases TLS density within the tumor, indicating that TLSs are induced and recruited during treatment, activating B cells to initiate anti-tumor immune responses." (PMID 39840050, 2024). "To confirm that this similarity is maintained with a different combination ICT, (anti-CTLA-4 and anti-PD-L1), we performed bulk TCRβ sequencing on tumours from treated animals and similarly found that TCRβ repertoires in tumours were highly related within animals, but not between animals." (PMID 38686178, 2024). "In the CT26 syngeneic tumor model, in which anti-CTLA4 and TU2218 were coadministered, complete regression was common, and a rechallenge assay was conducted to analyze whether immunological memory had been formed in these mice." (PMID 39105882, 2024). "Interestingly, tumor-infiltrating Tregs in cKO mice exhibited reduced CTLA4 expression, indicating compromised Treg function following Ku70 ablation." (PMID 39446493, 2024). "Also, due to the CRT expression found by X-ray irradiation, primary tumors and secondary inoculated tumors with the PLGA-R837@Cat treatment combined with CTLA-4 antibody showed complete tumor regression." (PMID 39769944, 2024). "Evaluating the relative levels of sCTLA-4:CTLA-4 in tumor types may be important in the context of CTLA-4-based immune checkpoint therapy." (PMID 38053333, 2024). "Therefore, treatment was set at 5 mg/kg of the VHHs or 12.5 mg/kg, an equimolar amount, of the anti-CTLA-4 antibody 9H10 administered on days 7, 10, and 13 post-tumor injection." (PMID 39149504, 2024). "Therefore, antitumor therapies that antagonize CTLA‐4 and/or PD‐1/PD‐L1 can attenuate the immune escape signal released by the tumor and enhance the host antitumor immune response." (PMID 38525112, 2024). "With a higher level of tumor neoantigens, more CTL will infiltrate the microenvironment, enhancing IFN-γ level, thus programmed death ligand-1 (PD-L1) molecules and cytotoxic T lymphocyte-associated antigen-4 (CTLA-4) increasing." (PMID 38887597, 2024). "Additionally, we investigated the clinical utility of PD-1 and CTLA-4 in determining key pathological tumor characteristics, including tumor size, disease stage, and multifocality." (PMID 38672574, 2024). "As the inhibitory roles of CTLA-4 and PD-1 in immune responses, including antitumor responses, are distinct, their effectiveness in cancer treatment depends significantly on the cancer type and tumor size." (PMID 38375475, 2024).
tumor (continued). "Interestingly low-dose RT enhanced the anti-tumor responses to ICIs (anti-PD-1 and anti-CTLA-4), promoting M1-polarization of macrophages, NK infiltration, and reduction in transforming growth factor beta (TGF-β) levels." (PMID 38033759, 2024). "This could suggest a role for CTLA-4 in tumour progression, possibly due to T-reg control over immune local response." (PMID 38893123, 2024). "This might reflect the immune escape of tumor and CTLA4-mediated regulation of immunity in the responders." (PMID 38637495, 2024). "Indeed, CTLA4/CUL5 DKO in CD8+ T cells showed further improved tumor control in vivo compared to CUL5 KO alone." (PMID 38242867, 2024). "We then asked whether combination with ICB is required for systemic anti-tumor immunity and observed tumor-specific abscopal effects with the monotherapy or when combined with anti-PD-1 or anti-CTLA-4." (PMID 39236156, 2024). "In contrast, RT and IL-12 applied to the primary tumors in combination with systemic srIL-2 and anti-CTLA-4 in a two-tumor model, induced eradication of 5 out of 5 of the primary tumors (mean volume 197 mm3), and 3 out of 5 of the distant tumors (mean volume 261mm3)." (PMID 39076988, 2024). "Dovitinib, an inhibitor of multiple receptor tyrosine kinases, is reported to induce the activation of tumor‐intrinsic SNAI1/2‐IFN‐γ signaling and suppress EMT in another recent study, which promotes T cell recruitment and makes mesenchymal‐like tumor to be sensitive to CTLA4 blockade." (PMID 39092293, 2024). "Furthermore, a tumor microenvironment-activated nanoassembly involving the coassembly of PD-L1- or CTLA-4-antagonizing aptamers and a glucose transporter one inhibitor was shown to significantly decrease PD-L1 N-linked glycosylation." (PMID 39080767, 2024). "This difference may be due to a different balance of immune cell subsets within the tumour microenvironment—such a higher abundance of FOXP3 + T-cells, or due to differences in the tumour immune microenvironment such as CTLA-4 expression." (PMID 38649964, 2024). "Clinical research on ICI therapy is advancing, starting with the most well-known ICMs CTLA-4 and PD-1, where blocking signalling through these molecules has been shown to promote T cell infiltration and expansion at the tumour site and to activate intratumoral natural killer (NK) cells." (PMID 39337605, 2024). "CTLA4 was found to inhibit T cell activation and proliferation, thereby diminishing tumor immunity." (PMID 38965571, 2024). "PDAC engages with CTLA-4 to inhibit T-cell activity and continue tumor growth." (PMID 38893220, 2024). "Similarly, Lujun Chen and others used the MC38 and CT26 tumour models to evaluate the therapeutic effects of cordycepin, CTLA-4 blockade, and their combination therapy." (PMID 38953102, 2024). "Finally, regarding the IC expression, the IM subtype exhibited an increased density of CTLA-4+ and PD-1+ TILs and an enrichment of PD-L1, PD-1, and CTLA-4 genes, along with high PD-L1 expression by tumor cells." (PMID 38893213, 2024). "Similarly, we observed significantly enhanced survival and significantly reduced tumor growth in ABx mice treated with anti-CTLA4 as compared to untreated ABx mice." (PMID 38500667, 2024). "An innovative humanized anti‐CTLA‐4 variant, designed to be more compact and optimized for Fc‐mediated antibody‐dependent cellular cytotoxicity (ADCC), has demonstrated enhanced tumor penetration and a more potent tumor immune response in comparison to conventional anti‐CTLA‐4 therapies." (PMID 38349050, 2024). "The inhibitory receptors expressed on T cells, interacting with their corresponding ligands expressed on antigen-presenting cells or tumor cells, such as PD-1/PD-L1, CTLA-4/CD86, TIM-3/Galectin-9, TIGIT/CD155, and BTLA/HVEM, play important roles in regulating T cell functions." (PMID 39329729, 2024). "Interestingly, however, the IFNGR1 signaling pathway in tumor cells has recently been shown to be essential for the efficacy of CTLA-4 and PD-1 ICB." (PMID 38982116, 2024).